DPEP1 (dipeptidase 1)
Diseases named in the same sentence as DPEP1 in open-access papers (continued):
Sharing a sentence is not in itself a finding about the gene and the disease.
glioma (3 papers, 2022 to 2025). A benign or malignant brain and spinal cord tumor that arises from glial cells (astrocytes, oligodendrocytes, ependymal cells). "To further validate the clinical relevance of DPEP1, we analyzed the The Cancer Genome Atlas-Glioblastoma-Low Grade Glioma (TCGA-GBM-LGG) dataset, revealing significantly higher expression of DPEP1 in isocitrate dehydrogenase (IDH)-wild type tumors compared to lower-grade gliomas with IDH mutation." (PMID 40319462, 2025). "We also explored the perturbation effects of these genes which suggested that the importance of DPEP1, G6PD, GGT1, GGT5, IDH1, and NFE2L2 for glioma cell survival." (PMID 38819225, 2024).
leukemia (3 papers, 2023 to 2024). A malignant (clonal) hematologic disorder, involving hematopoietic stem cells and characterized by the presence of primitive or atypical myeloid or lymphoid cells in the bone marrow and the blood. "Most of the protein hits could be identified in blood samples according to the HPA database; two of them, namely DPEP1 and SOST, were classified by HPA as upregulated in BC; and five of them were found to be upregulated in leukemia and myeloma: SOST, TXNRD1, PKLR, EPHA2, PLIN3." (PMID 38791048, 2024).
Sepsis (3 papers, 2021 to 2025). Sepsis is defined as life-threatening organ dysfunction caused by a dysregulated host response to infection. "Another up-regulated protein during sepsis inflammatory conditions is dipeptidase 1 (DPEP1), expressed on cells of key organs such as the kidney, liver, and lung." (PMID 38637839, 2024). "DPEP1 was recently identified as a neutrophil-binding receptor and targeting DPEP1 reduced mortality in murine models of sepsis, suggesting a role for DPEP1 in inflammation." (PMID 34887515, 2021).
ulcerative colitis (3 papers, 2023 to 2025). An inflammatory bowel disease involving the mucosal surface of the large intestine and rectum. "In another study of the transition from ulcerative colitis to ulcerative colitis-associated colorectal cancer, the role of DPEP1, CD74, and CLCA1 in the progression of the disease was identified." (PMID 38339232, 2024). "Two genes related to cellular metabolism (dipeptidase 1 (DPEP1) and sphingosine kinase 1 (SPHK1)) were found to be related to the PFOA-promoted formation of ulcerative colitis using our self-developed Metabolic Gene and Pathway Query software and Comparative Toxicogenomics Database (CTD)." (PMID 39722626, 2025).
Wilms tumor (3 papers, 2012 to 2020). An embryonal neoplasm characterized by the presence of epithelial, mesenchymal, and blastema components. "DPEP1 was identified as a tumor suppressor due to its decreased expression in Wilms’ tumor as compared to normal kidney tissue." (PMID 26824987, 2016).
atherosclerosis (2 papers, 2023 to 2025). A disease characterized by the build-up of fatty material and calcium deposition in the arterial wall resulting in partial or complete occlusion of the arterial lumen. "Rare cells expressing FB-like (I-cluster 12, Pi16+, Igfbp4+, and Dpep1+) or MΦ-like genes (I-cluster 14, Lgals3+, Cd68+, and Ptprc+) had low expression of the eYFP lineage label, suggesting that these cells were not derived from VSMCs, similar to what has been proposed in atherosclerosis." (PMID 40577585, 2025).
pancreatic cancer (2 papers, 2012 to 2016). "Further delineation of pathways that regulate DPEP1 expression in pancreatic cancer may provide insights into the genes and pathways associated with DPEP1 and facilitate the development of more effective therapeutic strategies for PDAC." (PMID 22363658, 2012). "To determine the effect of DPEP1 expression on the sensitivity of pancreatic cancer cell lines to gemcitabine, we examined cytotoxicity of gemcitabine on Panc1 and MIApaca2 cells after 96 h of drug exposure." (PMID 22363658, 2012). "We then explored the biological function of DPEP1, a predictor of patient outcome identified in our study, revealing its potential therapeutic significance in pancreatic cancer." (PMID 22363658, 2012). "To investigate the possible mechanism for the regulation of DPEP1 expression in pancreatic cancer, we examined the levels of DPEP1 in Panc1 cells in response to EGF (30 nM), MEK1/2 inhibitor AZD6244 (1.5 μM) and PI3K inhibitor LY294002 (1.5 μM)." (PMID 22363658, 2012). "In the present study, we have elucidated the function of DPEP1 in pancreatic cancer cells." (PMID 22363658, 2012). "Therefore, we provide evidence that DPEP1 plays a role in pancreatic cancer aggressiveness and predicts outcome in patients with resected PDAC." (PMID 22363658, 2012). "Future studies will investigate whether DPEP1 in stromal cells plays a role in pancreatic cancer development." (PMID 22363658, 2012). "Therefore, we examined if the expression of DPEP1 affects the cellular growth and invasion of pancreatic cancer cell lines." (PMID 22363658, 2012). "Interestingly, immunostaining of archival human pancreatic cancer tissues showed DPEP1 expression in both carcinoma cells and peritumoral stroma." (PMID 22363658, 2012). "Moreover, DPEP1 over-expression increases the sensitivity of pancreatic cancer cells to chemotherapeutic drug gemcitabine." (PMID 22363658, 2012). "Our study showed a marked reduction in DPEP1 expression in pancreatic tumors as compared with non-tumor tissues using both microarray and qPCR, which is consistent with the ONCOMINE data mining." (PMID 22363658, 2012).
schizophrenia (2 papers, 2021 to 2023). A major psychotic disorder characterized by abnormalities in the perception or expression of reality. "This indicates clinical re-purposing potential of Cilastatin, and other DPEP1 inhibitors, as treatments for schizophrenia, though further investigations are needed." (PMID 37034613, 2023).
B-cell acute lymphoblastic leukemia (1 paper, 2023). A neoplasm of lymphoblasts committed to the B-cell lineage, typically composed of small to medium-sized blast cells. "DPEP1 expression has significant increases in B-cell acute lymphoblastic leukemia that are related to progressive and relapsing disease." (PMID 38090559, 2023).
basal cell carcinoma (1 paper, 2025). A carcinoma involving the basal cells. "Beyond its potential as a CM therapeutic target, DPEP1 was identified as a candidate for treating other nonmelanoma tumors (OR = 0.767, 95% CI: 0.693–0.849, FDR < 0.01), such as basal cell carcinoma." (PMID 40988203, 2025).
breast lobular carcinoma (1 paper, 2016). An adenocarcinoma of the breast arising from the lobules. "Similarly, loss of DPEP1 expression correlates with breast lobular carcinomas." (PMID 26824987, 2016).
chronic kidney disease (1 paper, 2022). Impairment of the renal function secondary to chronic kidney damage persisting for three or more months. "Furthermore, a recent study identified single-nucleotide polymorphisms (SNPs) in close proximity to the DPEP1 gene to be frequently associated with AKI to chronic kidney disease progression in a large patient cohort." (PMID 35108055, 2022).
clear cell renal carcinoma (1 paper, 2015). A malignant epithelial neoplasm of the kidney characterized by the presence of lipid-containing clear cells within a vascular network. "A particularly interesting kidney-specific gene was DPEP1 (a dipeptidase) in light of the recently observation of elevated dipeptide levels in a subset of clear cell renal carcinoma tumors (manuscript in preparation)." (PMID 25961905, 2015).
ductal carcinoma (1 paper, 2012). "In order to determine the localization of DPEP1 protein, we performed immunohistochemical staining on paraffin sections, which showed that DPEP1 expresses in both ductal carcinoma cells and stromal fibroblast cells." (PMID 22363658, 2012).
endothelial dysfunction (1 paper, 2026). In vascular diseases, endothelial dysfunction is a systemic pathological state of the endothelium (the inner lining of blood vessels) and can be broadly defined as an imbalance between vasodilating and vasoconstricting substances produced by (or acting on) the endothelium. "Functionally, chronic Dpep1 inhibition by cilastatin and endothelium-specific Dpep1 knockdown attenuated neutrophilic vascular inflammation and rescued endothelial dysfunction in diabetic mice." (PMID 41930346, 2026).
esophageal cancer (1 paper, 2020). A primary or metastatic malignant neoplasm involving the esophagus. "The results showed that EPHA5, LOC100506136, RGS7, THBS4, SCGB1A1, and DPEP1 were dysregulated between esophageal cancer and normal control in GSE13898 validation dataset (all, P<0.05)." (PMID 32068233, 2020).
glioblastoma (1 paper, 2025). The most malignant astrocytic tumor (WHO grade IV). "Here, we identify that hypermetabolic glioblastoma lesions are marked by high tumor mutational burden, DPEP1-positive endothelial tip cells, and abundant proliferating tumor and endothelial cells." (PMID 40319462, 2025). "Subsequent analysis unveiled that the classical and mesenchymal glioblastoma subtype exhibited markedly elevated expression of DPEP1 relative to the proneural subtype." (PMID 40319462, 2025). "Clustering analysis identified 8 distinct clusters, with cluster 7 demonstrating the highest expression levels of DPEP1 within the glioblastoma tissue section." (PMID 40319462, 2025). "To delve into the downstream pathways and gain mechanistic insights into DPEP1, we employed spatial transcriptomics datasets (Visium, Glioblastoma, FFPE fixed, 10X Genomics)." (PMID 40319462, 2025). "IHC was employed to validate the spatial distribution of DPEP1 within the glioblastoma microenvironment, revealing localization predominantly at vascular tips and sprouting endothelial structure." (PMID 40319462, 2025). "DPEP1 expression correlates with pathways related to vascular development, neovascularization, and metabolic adaptation in glioblastomas." (PMID 40319462, 2025). "Our analysis revealed DPEP1 as one of the most significantly upregulated genes in hypermetabolic glioblastoma lesions compared to both kryo and akri lesions." (PMID 40319462, 2025). "Targeting DPEP1 with cilastatin significantly suppressed DPEP1 expression and reduced the angiogenic sprout area in both glioblastoma-derived vascular sprouts and mouse aortic ring assays without inducing toxicity, highlighting its potential as a therapeutic target." (PMID 40319462, 2025). "DPEP1 overexpression was localized to specific regions of glioblastoma lesions." (PMID 40319462, 2025). "Notably, high DPEP1 expression correlates with poor survival in glioblastoma patients across multiple cohorts, while CD34 expression showed no impact on patient survival." (PMID 40319462, 2025). "Importantly, we show in vitro DPEP1 inhibition impaired angiogenesis in glioblastoma-derived endothelial sprouts, revealing the therapeutic potential of dipeptidase 1 inhibition." (PMID 40319462, 2025). "Furthermore, we identify dipeptidase 1 as a novel vascular endothelial tip marker for hypermetabolic lesions in glioblastoma, facilitating angiogenesis and tumor metabolism by regulating transporter activities." (PMID 40319462, 2025).
Hyperglycemia (1 paper, 2026). An increased concentration of glucose in the blood. "Furthermore, the corticosteroid dexamethasone activated the shear stress-responsive GR/DPEP1 axis in vivo, yet exerted time-dependent vascular effects-acutely dampening neutrophilic inflammation, but chronically worsening hyperglycemia and aggravating vascular dysfunction." (PMID 41930346, 2026).
Hypertension (1 paper, 2023). The presence of chronic increased pressure in the systemic arterial system. "Shared genetic determinants of 7,073 metabolite–disease combinations represent a resource to better understand metabolic diseases and revealed connections of dipeptidase 1 with circulating digestive enzymes and with hypertension." (PMID 37277652, 2023).
IgA nephropathy (1 paper, 2022). "So far, several disease-specific biomarkers have been identified, such as CD44 in membranous nephropathy, dipeptidase 1 (DPEP1) and apolipoproteins in focal glomerulosclerosis (FSGS), and the laminin G-like 3 (LG3) fragments of endorepellin in IgA nephropathy." (PMID 36360378, 2022).
invasive ductal carcinomas (1 paper, 2017). "To determine the DPEP1 levels in BC development, we collected invasive ductal carcinoma specimens from 33 human BC patients and 11 adjacent normal tissues with informed consent." (PMID 28410206, 2017). "The DPEP1 mRNA level in invasive ductal carcinoma specimens was significantly higher than that of the adjacent normal tissues in women." (PMID 28410206, 2017).
kidney damage (1 paper, 2023). "Variants in CASZ1 and SHROOM3 were associated with microalbuminuria and UACR, and DPEP1 along with COL4A3 were common for kidney damage and UACR." (PMID 37446387, 2023). "Variants in CASZ1 and SHROOM3 were common for microalbuminuria and UACR, and DPEP1 along with COL4A3 were common for kidney damage and UACR (p < 0.001)." (PMID 37446387, 2023).
myocardial infarction (1 paper, 2024). Gross necrosis of the myocardium, as a result of interruption of the blood supply to the area, as in coronary thrombosis. "Following co-localization analysis for myocardial infarction (MI), we focused on four potentially relevant genes: DPEP1, CD8A, CD30 Ligand, and HDHD2." (PMID 39715222, 2024).
pancreatic adenocarcinoma (1 paper, 2012). "In addition to DPEP1, we also found that higher TPX2 expression is associated with poor outcome in two independent cohorts of resected PDAC patients, supporting the oncogenic role of TPX2 in several solid tumors including pancreatic adenocarcinoma." (PMID 22363658, 2012).
renal carcinoma (1 paper, 2023). A carcinoma arising from the epithelium of the renal parenchyma or the renal pelvis. "The study indicated that DPEP1 can be used as an independent predictor of prognosis in patients with RCC, and is expected to be used as a target of immunotherapy, providing a new avenue for the immunotherapy of renal cancer." (PMID 36866272, 2023).
Renal cyst (1 paper, 2024). A fluid filled sac in the kidney. "We found that multiple genes encoding enzymes in the γ-glutamyl cycle were highly downregulated in renal cysts, including γ-glutamyl transferase (GGT1, −14×), dipeptidase 1 (DPEP1, −32.5×), aminopeptidase N (ANPEP, −12×) and 5-oxoprolinase (OPLAH, −2.6×)." (PMID 39000280, 2024).
squamous cell carcinoma (1 paper, 2025). A carcinoma arising from squamous epithelial cells. "Remarkably, carcinogen-treated Dpep1-null mice develop multiple, large, plaque-like, locally invasive adenocarcinomas and squamous cell cancers in the distal colon." (PMID 40178918, 2025). "Of note, 2 distinct subtypes of invasive tumor, both ACA and squamous cell carcinoma (SCC), were present in DPEP1-KO mice." (PMID 40178918, 2025).
Ureteral obstruction (1 paper, 2021). Obstruction of the flow of urine through the ureter. "Dpep1 mutant mice also showed lesser kidney damage when compared to controls in the unilateral ureteral obstruction model." (PMID 34426578, 2021).
tumor (27 papers, 2012 to 2025). "IHC analysis of FH-deficient RCC showed that GGT1 was expressed in the tumor cells, whereas DPEP1 was primarily confined to the normal adjacent tissues." (PMID 37053010, 2023). "The fact that a higher DPEP1 expression level is associated with better patient outcome indicated its possible inhibitory role in tumor aggressiveness." (PMID 22363658, 2012). "A lower DPEP1 expression or a higher TPX2 expression in tumor was associated with poor survival in the Maryland validation cohort (P = 0.016 and P = 0.007 respectively, Kaplan-Meier log-rank test), consistent with our results in the Germany test cohort." (PMID 22363658, 2012). "DPEP1 expression was independently associated with cancer-specific mortality when adjusted for tumor stage and resection margin status in both univariate (hazard ratio = 0.43, 95%CI = 0.24–0.76, P = 0.004) and multivariate analyses (hazard ratio = 0.51, 95%CI = 0.27–0.94, P = 0.032)." (PMID 22363658, 2012). "Although it is perhaps surprising that DPEP1-KO mice had a greater tumor burden, this is reflective of patients whose MSI-H CRCs tend to be larger at presentation than their MSS counterparts." (PMID 40178918, 2025). "After AOM/DSS treatment, DPEP1-KO mice had a markedly greater number of tumors than WT mice, as well as a greater tumor volume per mouse." (PMID 40178918, 2025). "DPEP1’s role in angiogenesis, metabolism, and tumor progression highlights its potential as a biomarker and therapeutic target." (PMID 40319462, 2025). "To further investigate the role of DPEP1 in altering the tumor phenotype, we examined a number of relevant proteins by immunofluorescence." (PMID 40178918, 2025). "The difference in tumor number and burden between WT and DPEP1-KO mice was still significant when only considering Ads and ACAs, highlighting that the presence of SCC was not the sole contributor in observed differences in tumor number and burden." (PMID 40178918, 2025). "Taken together, these data provide evidence that DPEP1 has a causal role in immune exclusion, which we define as a paucity of CD8+ T cells in the tumor proper, and its expression appears to be critical for the maintenance of an MSS phenotype." (PMID 40178918, 2025). "The downregulated genes (DEPTOR, DPEP1, NAT8, and SUSD2) in the tumor and thrombus were associated with a worse survival rate when the gene was less expressed in the tumor, and the same correlation was observed for the upregulated genes (PLOD2 and SLC7A5)." (PMID 37328520, 2023). "Several reports assessed the expression levels of DPEP1 in various tumor cells and revealed opposite patterns depending on the tumor type." (PMID 36186450, 2022). "Knockdown of DPEP1 significantly inhibited tumor growth as shown by luciferase photon flux and tumor volumes at different time points after implantation." (PMID 31541079, 2019). "Meanwhile, the analysis of Gene Expression Omnibus (GEO) database (GSE75271) revealed that DPEP1 was drastically upregulated in HB tissues in comparison with that in non-tumor control tissues at the mRNA level." (PMID 31541079, 2019). "Fluorescence images demonstrated that DPEP1 knockdown resulted in significantly decreased tumor size." (PMID 31541079, 2019). "Silencing DPEP1 inhibited HB cell proliferation, migration, and invasion in vitro, and inhibited HB tumor development in vivo." (PMID 31541079, 2019). "In this current study, we found the upregulated expression of DPEP1 in HB patient tumor tissues and HB cell lines." (PMID 31541079, 2019). "In current study, we examined the expression levels of DPEP1 mRNA in 27 normal/tumor tissue pairs by quantitative real-time polymerase chain reaction (qRT-PCR) analysis." (PMID 26824987, 2016). "Several reports assessed the expression levels of DPEP1 mRNA in a variety of cancer cells and revealed opposite patterns depending on the tumor type." (PMID 26824987, 2016).